U6 (U6 spliceosomal RNA )
Gene: Small nuclear RNA gene on chromosome 2 (47,781,379 to 47,781,465, forward strand). Ensembl gene ENSG00000283502.
Homologues: Paralogues in human: RNU6-1145P (87% identical), RNU6-1316P (87% identical), RNU6-1075P (86% identical), RNU6-29P (86% identical), RNU6-38P (86% identical), RNU6-393P (86% identical), RNU6-40P (86% identical), RNU6-434P (86% identical), RNU6-44P (86% identical), RNU6-1031P (85% identical), RNU6-20P (85% identical), RNU6-25P (85% identical), and 1288 more.